IGF1 (insulin like growth factor 1)
Diseases named in the same sentence as IGF1 in open-access papers (continued):
Sharing a sentence is not in itself a finding about the gene and the disease.
endometrial cancer (continued). "Overexpression of IGF1 by tumor-associated macrophages promotes the carcinogenesis of epithelial ovarian cancer cells, whereas our study found a significant downregulation of IGF1 expression in endometrial cancer compared to the control." (PMID 34925436, 2021). "OR5H2 emerged as a new target for positive regulation by IGF1, with potential relevance in endometrial cancer biology." (PMID 34204736, 2021). "The insulin-like growth factor-1 (IGF1) axis has an important role in endometrial cancer biology and emerged as a promising therapeutic target in oncology." (PMID 34204736, 2021). "Our data demonstrate that the OR5H2 gene constitutes a novel target for IGF1 action in endometrial cancer." (PMID 34204736, 2021). "The downregulation of IGF-1 was also found in endometrial cancer specimens compared to the adjacent normal specimens in Soufla’s study, which seems to comprise the main features of endometrial carcinogenesis." (PMID 32641130, 2020). "In this type of cancer, the studies on the role of IGF1 mRNA isoforms only concern endometrial cancer cells in vitro (KLE)." (PMID 32977489, 2020). "YAP inhibitors or metformin alone only partially inhibited the function of insulin and IGF1 in endometrial cancer cells, while their combination completely blocked the effects of insulin." (PMID 33178014, 2020). "The expression of insulin and IGF-1 was significantly increased in diabetic patients, and high insulin levels were an independent factor of endometrial cancer." (PMID 31440472, 2019). "In summary, our study has identified the ZYG11A gene as a new downstream target for IGF1 action, with potential relevance in endometrial cancer biology." (PMID 31320996, 2019). "How insulin and IGF-1 interact with estrogen in signaling pathways to promote the development of endometrial cancer warrants further investigation." (PMID 31440472, 2019). "Increased insulin and IGF-1 can stimulate the proliferation of endometrial cancer cells by binding to IR and IGF-1 receptors (IGF-1R) and activating downstream signaling pathways." (PMID 31440472, 2019). "Our data suggest that the ZYG11A gene constitutes a novel target for IGF1 action in endometrial cancer cells." (PMID 31320996, 2019). "It has been reported that plasma hyperglycemia and high levels of IGF-1 in patients with endometrial cancer can be reversed by conventional doses of metformin." (PMID 31440472, 2019). "The present study was designed to identify the entire set of genes that are differentially activated by glargine or detemir, in comparison to native insulin and IGF1, in both Type I and II endometrial cancer cell lines." (PMID 29615978, 2018). "In recent studies, we provided evidence that certain insulin analogs elicit differential activities in endometrial cancer cells in comparison to regular insulin or IGF1." (PMID 29615978, 2018). "The present study was aimed at identifying the entire set of genes that are differentially activated by insulin glargine or detemir, in comparison to insulin and IGF1, in Type 1 and Type 2 endometrial cancer cell lines (ECC-1 and USPC-1, respectively)." (PMID 29615978, 2018). "Cixutumumab, a fully human monoclonal antibody against IGF1R, inhibited IGF1-mediated biological actions and cell signaling events in four endometrial carcinoma-derived cell lines." (PMID 29922232, 2018). "The proliferative effects of androgen have been linked to enhancement of EGF action, increased expression of genes involved in IGF-1 and Wnt signaling or to endometrial cancer cell proliferation through activation of the oncogene c-myc." (PMID 27384477, 2016).
endometrial cancer (continued). "Studies by several groups have shown that IGF1 has a significant role in both Type I and II endometrial cancers, emphasizing the importance of altered IGF1R gene expression in the development of a malignant phenotype." (PMID 24904527, 2014). "Increasing levels of IGF-1 and of IGF-binding protein-1 have been associated with endometrial cancer risk, particularly in older overweight women." (PMID 17912243, 2007). "Leptin and IGF 1 and 2 were not linked to endometrial cancer risk, except for IGF1 and 2 increasing the risk of type 1 endometrial cancer in obese individuals (p = 0.005 and 0.004, respectively)." (PMID 38339282, 2024). "This hypothesis was confirmed by in vitro experiments showing that IGF1 stimulated the OR5H2 mRNA levels by 4.2- to 7.3-fold in two endometrial cancer cell lines." (PMID 34204736, 2021). "Hence, we supposed that the altered expression and variants of the FTO gene contribute to the progression and prognosis of women with endometrial cancer through energy metabolism as well as IGF1 signaling." (PMID 34149936, 2021). "The identification of OR5H2 as an IGF1-dependent, mitogenic factor in endometrial cancer might help in these efforts." (PMID 34204736, 2021). "We evaluated the information provided in articles published in English using a combination of keywords relevant to the proper adipokines, angiogenic growth factors (VEGF, FGF and IGF-1), inflammatory cytokines (TNFα, IL-6, IL-1β and IL-8) and endometrial cancer." (PMID 33799622, 2021). "Our study showed a significant reduction in IGF1 expression in endometrial cancer compared to the control, which may be due to increased let-7a, let-7f, let-7g, miR-625 and miR-331-3p activity." (PMID 31795319, 2019). "In endometrial cancer cell cultures, metformin treatment lowers secretion of insulin-like growth factor (IGF-1), downregulates expression of insulin receptor and IGF-1R, inhibits phosphorylation of IGF-1R, and increases expression of insulin-like growth factor-binding protein 1 (IGFBP-1)." (PMID 30211120, 2018). "In conclusion, our study does not show any evidence of an overall association between endometrial cancer risk and serum levels of IGF-1, IGFBP-1, IGFBP-3, and insulin." (PMID 14583772, 2003). "Interestingly, compared to control subjects where IGF levels decreased after menopause, post-menopausal women in the study group showed elevated IGF1 and IGF2 levels, suggesting a potential influence of endometrial cancer on the IGF system, particularly after menopause." (PMID 38339282, 2024). "In view of the epidemiological and clinical correlations between the insulin/IGF1 signaling pathway and endometrial cancer risk and to explore the potential regulation of ZYG11A by IGF1, we investigated the expression of this gene in endometrial cancer-derived cell lines." (PMID 31320996, 2019). "This will be achieved by evaluating the proliferative effects of PCOS serum, IGF-1, and IGF-1 antagonist on human endometrial cancer 1-A and 1-B cell lines, with a comparison to controls (using serum from women without PCOS and cell culture media)." (PMID 37988160, 2023). "In the same study, progesterone was shown to downregulate a number of signaling pathways known to play an important role in the EMT of endometrial cancer, including PI3K, TGFβ, IGF-1, and EGF." (PMID 36052252, 2022). "An optimized culture condition by reducing the p38i concentration and adding insulin-like growth factor 1 (IGF1), HGF, and lipids enhanced the efficiency of organoids generated from endometrial cancers." (PMID 32552764, 2020). "PI3K/Akt regulates insulin/IGF1 signaling, and IRS1/2 expression in patients with endometrial cancer is positively correlated with YAP/TAZ." (PMID 33178014, 2020).
endometrial cancer (continued). "Decreased expression of IGF1 and MYLK, as well as SOD2 overexpression, were observed in endometrial cancer using both mRNA microarrays and RT-qPCR." (PMID 31795319, 2019). "Metformin, an antidiabetic drug, is effective for endometrial cancer through inhibition of the PI3K-Akt-mTOR pathway by activating LKB1-AMPK and reduction of insulin and insulin-like growth factor-1 due to AMPK activation." (PMID 25734181, 2015). "Pathologic disruption of mRNA co-expression patterns supports the notion of a cross talk between IGF1, EGF, and FGF2 signaling pathways in the promotion of endothelial cell proliferation and differentiation of endometrial cancer." (PMID 24904527, 2014). "Previous studies have demonstrated that insulin-like growth factor 1 (IGF-1) and IGF-2 promote cell proliferation in endometrial cancer cells, while metformin reverses this effect and inhibits cell proliferation." (PMID 25289085, 2014). "IGF1 and IGF2 do not show significant associations with the risk of endometrial cancer in the entire population." (PMID 38339282, 2024). "employed transcriptome sequencing technology to analyze 5 pairs of endometrial cancer tissues and normal endometrial tissues, revealing downregulation of ID1, IGF1, GDF7, SMAD9, TGF-β, and WNT4 expression alongside upregulation of GDF5, INHBA, and ERBB4 in endometrial cancer." (PMID 38239355, 2023). "To evaluate our hypothesis that UGT2B15 is a target for inhibitory regulation by IGF1, we chose to measure UGT2B15 mRNA levels in endometrial cancer cells." (PMID 35626664, 2022). "Estrogen receptor transcriptional activity can be induced by signaling by insulin-like growth factor 1 even in the absence of estradiol, which increases the incidence of endometrial cancer." (PMID 34501584, 2021). "Insulin-like growth factor-1 and epidermal growth factor (EGF) downregulation and fibroblast growth factor-2 (FGF2) up-regulation seem to constitute key features of endometrial cancer progression, as demonstrated in a collection of 30 cancer specimens that were compared to normal adjacent tissue." (PMID 24904527, 2014). "This study examined a set of six markers, namely, adiponectin, leptin, IL6, TNFα, IGF1, and IGF2 and compared them between fifty age-matched endometrial cancer patients (study group) and non-cancer patients with benign gynaecological conditions (control group)." (PMID 38339282, 2024).
gastric cancer (75 papers, 1996 to 2025). A primary or metastatic malignant neoplasm involving the stomach. "MMP11 is significantly expressed in gastric cancer cells and has been implicated in enhancing tumor growth and invasion through the modulation of IGF-1 signaling." (PMID 39895782, 2025). "Of those, the subtype characterized by IGF1-overexpressing CAFs was specifically associated with chemo-resistance and gastric cancer recurrence." (PMID 38892104, 2024). "A Japanese study reported that two IGF1 SNPs (rs1520220 and rs2195239) were significantly associated with relapse-free survival in gastric cancer patients who had undergone curative gastrectomy." (PMID 27144430, 2016). "However, the blood insulin‐like growth factor 1 (IGF‐1) level is elevated by milk consumption, and this had been linked to an increase in stomach cancer." (PMID 37457194, 2023). "The IGF-1 signaling pathway has been implicated in gastric cancer development." (PMID 25006674, 2014). "However, milk consumption increases serum IGF-1, which has been associated with increased gastric cancer." (PMID 25006674, 2014). "Serum IGF-1 levels were considerably lower in patients than in controls in a study that included 20 patients with gastric cancer and 20 healthy controls." (PMID 41303367, 2025). "Clinical studies have shown that serum IGF-1 levels are dysregulated in breast, ovarian, pancreatic, and gastric cancers." (PMID 41303367, 2025). "ROC analyses revealed that IGF-1, IGFBP-4, and IGFBP-5 have good discriminatory properties in the diagnosis of gastric cancer, while PAPP-A offers low diagnostic value." (PMID 41303367, 2025). "In the gastric cancer serum sample, IGF-1 and IGFBP-5 were the most accurate biomarkers in differentiating between gastric cancer patients and healthy individuals." (PMID 41303367, 2025). "The findings showed that IGF-1 levels were significantly decreased in the gastric cancer group, while IGFBP-4 levels were significantly increased." (PMID 41303367, 2025). "In our study, IGF-1 levels were significantly lower in gastric cancer patients compared to the healthy control group." (PMID 41303367, 2025). "It identifies that cancer-associated fibroblasts (CAF) secrete lysyl oxidase (LOX), which activates the TGFβ signaling pathway and increases insulin-like growth factor 1 (IGF1) levels in gastric cancer cells." (PMID 39897050, 2025). "Conserved common CAF clusters included myCAF (the most abundant CAF subset in all tumour types except gastric cancer), IGF1 + CAF and proto-CAF." (PMID 39757146, 2025). "IGF1 induced SOX12 expression via the PI3K/AKT/CREB pathway, forming an IGF1/CREB/SOX12 feedback loop that contributed to gastric cancer metastasis." (PMID 40638546, 2025). "IGF-1 plays a critical role in the stimulation of gastric cancer cell proliferation, angiogenesis, survival, and resistance to apoptosis." (PMID 39767693, 2024). "IGF1 secreted by CAFs induces drug-resistant phenotypes in gastric cancer cells through IGF1-α6β4 integrin ligand–receptor binding and activation of EMT biological processes." (PMID 38892104, 2024). "The IGF1 signal pathway is highly activated in some subtype of gastric cancer(GC) that exhibits poor survival and chemotherapy resistance." (PMID 36774408, 2023). "SOX12 transcriptionally targets matrix metallopeptidase 7 (MMP7) and insulin-like growth factor 1 (IGF1) to facilitate gastric cancer metastasis." (PMID 35485164, 2022). "Previous studies have demonstrated that lncRNA NR2F1-AS1 can influence breast and gastric cancer progression by activating insulin-like growth factor-1 (IGF-1)/IGF-1R/ERK, MAP3K2, and AKT3, which crosstalk with AKT." (PMID 35283481, 2022). "To further clarify the role of PI3K/AKT in hsa_circ_0000520 inhibition of Herceptin resistance in gastric cancer, we used IGF‐1 (an activator of PI3K/AKT) to treat NCI‐N87R cells with hsa_circ_0000520 transfection and Herceptin treatment." (PMID 32701211, 2020).
gastric cancer (continued). "In gastric cancer, IGF1/IGF1R/STAT3 signaling‐inducible IFITM2 promotes gastric cancer growth and metastasis." (PMID 32851683, 2020). "Many target mRNAs of miR-29a, including but not limited to VEGFA in gastric carcinoma and IGF-1 in cardiac endothelial cells, have been discovered." (PMID 32733638, 2020). "Treatment with the demethylation agent 5-azacytidine (5-AzaC) restored expression of IGF1 in two of EP-like gastric cancer cells (MKN28 and SNU16)." (PMID 29725014, 2018). "More importantly, MP subtype gastric cancer cells were more sensitive to inhibition of IGF1/IGF1R pathway." (PMID 29725014, 2018). "When IGF-1 activate mTORC1 pathway in BGC-823 gastric cancer cells, endogenous Skp2 was phosphorylated at Ser64." (PMID 28446188, 2017). "The prosurvival effect of IGF-1 was more pronounced for gastric cancer cells isolated directly from patients than for cell lines which shows that IGF-dependence is an inherent characteristic of gastric cancer cells and is not acquired during culture." (PMID 27437872, 2016). "The data indicate that IGF-1 stimulated proliferation of gastric cancer cells is mediated through the type I IGF receptor and involves activation of the Ras/Raf/MAP-kinase pathway." (PMID 27437872, 2016). "Proliferation of gastric cancer cells was stimulated by IGF-1 and the stimulation was decreased by inhibition of the Ras/Raf/MAP-kinase pathway." (PMID 27437872, 2016). "MiR-7, which negatively controls the function of α-synuclein mRNA, also serves as an anti-metastatic miRNA in gastric cancer by targeting Insulin-like Growth Factor-1 (IGF-1)." (PMID 23060898, 2012). "GH, possibly via insulin-like growth factor (IGF)-1, exerts its effect during development of primary gastric cancer." (PMID 23554765, 2012). "Higher IGF-1 concentrations have been observed in patients with gastric cancer than in healthy controls." (PMID 19190635, 2009). "Moreover, FLOT1 mediates the levels of heterotypic signaling molecules, including TNF-α, EGF, HGF, and IGF1, across various cancers, such as breast, prostate, and gastric cancer, and oral squamous cell carcinoma." (PMID 40335491, 2025). "Moreover, differential gene expression analyses also found that high PAPP-A expression was associated with an increase in IGF-1 and IGFBP-4 in gastric cancer." (PMID 41303367, 2025). "Similarly, in a meta-analysis conducted in 2021, IGF-1 levels were lower in gastric cancer patients than in healthy individuals." (PMID 41303367, 2025). "Overall, these results demonstrate that the IGF signaling pathway plays a critical role in the pathogenesis of gastric cancer and that IGF-1, IGFBP-4, and IGFBP-5, in particular, may serve as potential biomarkers for clinical applications." (PMID 41303367, 2025). "All gastric cancer patients had higher IGF-1 serum levels compared with healthy participants." (PMID 41303367, 2025). "Data indicated that the serum IGF‐1 levels in patients with stomach cancer might be noticeably higher than normal levels." (PMID 37457194, 2023). "Previous study has proven that the epithelial-mesenchymal transition (EMT) process of gastric cancer cells could be induced by IGF-1 through the IGF-1R/STAT3 signaling pathway so that cancer cells would achieve metastasis." (PMID 34804946, 2021). "In order to investigate whether hsa_circ_0000520 can play a role by regulating the PI3K‐Akt signaling pathway, the study will treat gastric cancer cells with PI3K‐Akt signaling pathway activator IGF‐1." (PMID 32701211, 2020). "Furthermore, promoter regions of IGF1 were concomitantly demethylated upon treatment of 5-AzaC, supporting promoter hypomethylation as one of the mechanisms for activation of the IGF1/IGF1R pathway in gastric cancer." (PMID 29725014, 2018). "Gastric cancer cell lines were first grouped according to expression of IGF1." (PMID 29725014, 2018).